NUAK1 (NUAK family kinase 1)
Diseases named in the same sentence as NUAK1 in open-access papers (continued):
Sharing a sentence is not in itself a finding about the gene and the disease.
liver cancer (4 papers, 2017 to 2023). An epithelial or non-epithelial malignant neoplasm that arises from the liver. "We demonstrated a positive regulatory relationship between HOTAIR and NUAK1 in liver cancer tissues and cells and showed that HOTAIR regulates the miR-145-5p /NUAK1 axis through PRC2 (EZH2)." (PMID 37576402, 2023). "In this study, through transcriptome sequencing data and in vitro experiments, we found that HOTAIR were more highly expressed and there is significantly positive relationship between HOTAIR and NUAK1 in liver cancer tissues and cell lines." (PMID 37576402, 2023). "The results showed that inhibition of NUAK1 reduced the invasion and migration ability of liver cancer cells." (PMID 37576402, 2023). "Here we demonstrated that HOTAIR and NUAK1 were positively correlated in liver cancer tissues and cell lines and that the addition of NUAK1 inhibitor reversed the effect of high HOTAIR expression on EMT-related proteins." (PMID 37576402, 2023). "We examined the expression of NUAK1 in five liver cancer cell lines and found that NUAK1 was highly expressed in these cell lines." (PMID 37576402, 2023). "In this sudy, through transcriptome sequencing data and in vitro experiments, we found that HOTAIR were more highly expressed and there is significantly positive relationship between HOTAIR and NUAK1 in liver cancer tissues and cell lines." (PMID 37576402, 2023). "We also showed that HOTAIR recruiting and binding PRC2 (EZH2) epigenetically represses miR-145-5p, which controls the target NUAK1, thus contributing to liver cancer cell-EMT process and accelerating tumor metastasis." (PMID 37576402, 2023). "In conclusion, here we found that the higher expression of HOTAIR and NUAK1 and the lower expression of miR-145 promote the invasion and metastasis of liver cancer cells." (PMID 37576402, 2023). "Additional experiments revealed that HOTAIR knockdown, miR-145-5p upregulation and NUAK1 inhibition all repressed migration, invasion and metastasis and reversed liver cancer cell-EMT in SNU-387 and HepG2." (PMID 37576402, 2023). "We also found that NUAK1 was highly expressed by qPCR in 30 pairs of liver cancer tissues compared with adjacent normal tissues and that expressions of HOTAIR and NUAK1 were positively correlated." (PMID 37576402, 2023). "Therefore, our study findings reveal the involvement of the HOTAIR/PRC2/miR-145-5p/NUAK1 axis in the invasion and metastasis of liver cancer cells." (PMID 37576402, 2023). "Together these results indicate that NUAK1 is highly expressed in liver cancer tissues and cells and may affect invasion and metastasis by inducing EMT." (PMID 37576402, 2023). "To examine whether HOTAIR regulates EMT in liver cancer cells through NUAK1, we transfected cells with the HOTAIR overexpression plasmid (P-HOTAIR) followed by addition of the NUAK1 inhibitor HTH-01-015 and then detected EMT markers E-cadherin, N-cadherin, and Vimentin by western blot." (PMID 37576402, 2023). "To evaluate the role of NUAK1 in liver cancer invasion and migration, we next used HTH-01-015, an inhibitor of NUAK1, in transwell and scratch assays in SNU-387 and HepG2 cells." (PMID 37576402, 2023). "Our findings indicate that HOTAIR/miR-145-5p/NUAK1 axis acts as an EMT regulator and may be candidate prognostic biomarker and targets for new therapies in liver cancer." (PMID 37576402, 2023). "In addition, HOTAIR also epigenetically downregulates miR-145-5p by binding to PRC2 (EZH2) to activate its target gene NUAK1, thereby promoting EMT in advanced stages of liver cancer." (PMID 37576402, 2023). "To explore whether miR-145-5p regulates the expression of NUAK1 in liver cancer cells, we next transfected miR-145 mimic and miR-145 inhibitor in SNU-387 and HepG2 cells and examined NUAK1 expression by western blot analysis." (PMID 37576402, 2023).
liver cancer (continued). "Together our results suggest that HOTAIR may regulate the miR-145-5p /NUAK1 axis through PRC2 to induce the EMT process and enhance the invasion and metastasis of liver cancer cells." (PMID 37576402, 2023). "However, the role of NUAK1 in liver cancer is not yet clear." (PMID 37576402, 2023).
serous ovarian cancer (4 papers, 2016 to 2022). "Nua kinase 1 (NUAK1) was identified in multigene signatures of survival and suboptimal debulking in high-grade serous ovarian cancer (HGSOC)." (PMID 27833898, 2016). "By examining spheroids generated from high-grade serous ovarian cancer (HGSOC) cells lines OVCAR8 and OVCAR5, we found that NUAK1 protein levels are down-regulated in spheroids when compared to adherent cells." (PMID 32429240, 2020).
tauopathies (4 papers, 2018 to 2025). "Geneticreduction of NUAK1 expression has notably been shown to lower totallevels of human tau in a tauopathy mouse model, identifying this kinaseas a potential therapeutic target for neurodegenerative disease." (PMID 39967649, 2025). "Of recent interest is the possibility that increased activity of the AMP-activated protein kinase (AMPK)-related kinase, NUAK1, in AD and primary tauopathies, results in the specific phosphorylation of tau at Ser356." (PMID 38175261, 2024). "NUAK1, one of the AMP-activated protein kinase (AMPK)-related kinases, was reported to play an important role in regulating tau levels, indicating that NUAK1 to be a novel therapeutic entry point for tauopathies." (PMID 37236919, 2023). "This work highlighted NUAK1 as an attractive target for therapeutic development in primary tauopathies, opening important questions about whether similar strategies could be applicable to secondary tauopathies such as AD." (PMID 38175261, 2024).
cholangiocarcinoma (3 papers, 2017 to 2023). A carcinoma that arises from the intrahepatic biliary tree (intrahepatic cholangiocarcinoma) or from the junction, or adjacent to the junction, of the right and left hepatic ducts (hilar cholangiocarcinoma). "Let-7a and miR-1182 downregulate NUAK1 mRNA, but have reduced expression in cholangiocarcinoma, leading to aberrant NUAK1 expression." (PMID 36766701, 2023).
head and neck squamous cell carcinoma (3 papers, 2014 to 2022). A squamous cell carcinoma that arises from any of the following anatomic sites: lip and oral cavity, nasal cavity, paranasal sinuses, pharynx, larynx, and salivary glands. "miR-203 controls head and neck squamous cell carcinoma metastasis by targeting a network of prometastatic proteins, including LASP1, SPARC, and NUAK1." (PMID 29262657, 2017).
lung carcinoma (3 papers, 2016 to 2023). "NUAK1 may activate the canonical NF-κB pathway via phospho-RelA in the lung cancer cell line A54972." (PMID 35194062, 2022). "Moreover, NUAK1 inhibits apoptosis and promotes proliferation and Myc expression in colon, liver, and lung cancer." (PMID 26882562, 2016).
autism spectrum disorder (2 papers, 2018 to 2024). A spectrum of developmental disorders that includes autism, and Asperger syndrome. "NUAK1 is a candidate gene for autism spectrum disorder (ASD), attention-deficit/hyperactivity disorder (ADHD) and intellectual disability." (PMID 38438384, 2024).
bladder cancer (2 papers, 2020 to 2023). "Thus, SNHG6 accelerates bladder cancer cell progression through miR‐125b/NUAK1 and miR‐125b/Snail1/2 pathways." (PMID 32518528, 2020). "Their data suggested that overexpressed SNHG6 induces EMT through upregulating Snail1/2 and promotes migration and invasion of bladder cancer cells by sponging miR‐125b, thereby activating the target gene of miR-125b-novel (nua) kinase family 1 (NUAK1), also known as ARK5." (PMID 32518528, 2020).
breast tumors (2 papers, 2018 to 2020). "Thus, NUAK1 inhibition may be an effective strategy for precision treatment of PTEN-deficient breast tumors." (PMID 29566768, 2018). "Moreover, analysing miR-622 and NUAK1 expression in each breast tumour subtype of this dataset, we found that this inverse correlation occurs specifically in the normal-like subtype (r = −0.332; p = 0.04)." (PMID 32418991, 2020).
cognitive deficits (2 papers, 2018 to 2023). "NUAK1+/− mice display some features associated with the autistic clinical spectrum, including disruption of social novelty preference, moderate cognitive deficits, and a reduction in the PPI reflecting a defect of sensory gating." (PMID 30327473, 2018).
colorectal tumors (2 papers, 2021 to 2023). "This study found that NUAK1 is a key component of the antioxidant stress response pathway, and the absence of NUAK1 can inhibit the formation of colorectal tumors." (PMID 33505587, 2021).
cutaneous melanoma (2 papers, 2014 to 2018). A primary melanoma arising from atypical melanocytes in the skin. "NUAK1 is phosphorylated by LKB1 (Liver Kinase B1), which carries somatic mutations in some cases of cutaneous melanoma." (PMID 29963229, 2018).
dementia (2 papers, 2023). Loss of intellectual abilities interfering with an individual's social and occupational functions. "Four genes (FGFBP2, PRSS23, TGFBR3, NUAK1) out of the 5 top IL-7Rαlow aging genes remained differentially expressed with decreased relative gene expression in the dementia group compared to the MCI group." (PMID 38042785, 2023). "Four genes (FGFBP2, PRSS23, TGFBR3, NUAK1) out of 5 top IL-7Rαlow aging genes remained differentially expressed at the P < 0.05 significance level after Šidák correction with decreased relative gene expression in the dementia group compared to the MCI group." (PMID 37066364, 2023).
diabetes (2 papers, 2018 to 2026). "As such, NUAK1 may play key roles in multiple diseases ranging from neurodegeneration to diabetes and metastatic cancer." (PMID 29106388, 2018).
idiopathic pulmonary fibrosis (2 papers, 2024 to 2025). Idiopathic pulmonary fibrosis (IPF) is a nonneoplastic pulmonary disease that is characterized by the formation of scar tissue within the lungs in the absence of any known cause. "Network pharmacology showed that the NUAK1 gene may be involved in the differentiation process of T helper cell subsets and thus participate in the occurrence and development of pulmonary fibrosis." (PMID 38774751, 2024). "Our study also suggests that NUAK1 may play a pivotal role in pulmonary fibrosis." (PMID 38774751, 2024). "The results showed that the expression levels of NUAK1 and CD8 in normal lung tissue were significantly lower than those in pulmonary fibrosis lung tissues (P<0.05 in both cases)." (PMID 38774751, 2024).
lymph node metastasis (2 papers, 2016 to 2023). "Importantly, NUAK1 expression was well correlated with histological differentiation, invasion pattern, and lymph node metastasis." (PMID 26882562, 2016). "Interestingly, NUAK1 expression was well correlated with histological differentiation, invasion pattern, and lymph node metastasis." (PMID 26882562, 2016).
pancreatic ductal adenocarcinoma (2 papers, 2023 to 2025). An infiltrating adenocarcinoma that arises from the epithelial cells of the pancreas. "Our analysis identifies a significant association of elevated NUAK1 expression with poor outcome in pancreatic ductal adenocarcinoma (PDAC)." (PMID 36975767, 2023). "Our previous work revealed increased expression of NUAK1 protein in a cohort of pancreatic ductal adenocarcinoma (PDAC) patient samples." (PMID 36975767, 2023). "Reasoning that MYC is a key effector of RAS pathway signalling and the GTPase KRAS is almost uniformly mutated in pancreatic ductal adenocarcinoma (PDAC), we investigated whether this cancer type exhibits a functional requirement for NUAK1." (PMID 36975767, 2023). "Several groups have shown that MYC is a critical effector of mutant KRAS in pancreatic ductal adenocarcinoma (PDAC), prompting us to examine if NUAK1 might be required to support oncogenic proliferation in this context." (PMID 36975767, 2023).
Anxiety (1 paper, 2018). Intense feelings of nervousness, tension, or panic often arise in response to interpersonal stresses. "We observed spontaneous activity through Open Field sessions but did not detect any differences between WT and NUAK1+/− mice in behaviors classically associated with anxiety or repetitive behavior." (PMID 30327473, 2018).
atherosclerosis (1 paper, 2024). A disease characterized by the build-up of fatty material and calcium deposition in the arterial wall resulting in partial or complete occlusion of the arterial lumen. "Considering the notion that restraining NF-κB signaling would dampen inflammatory signaling, this might indicate a possible protective role for NUAK1 in atherosclerosis." (PMID 38892400, 2024). "However, related to the scope of this review, to our knowledge, no information is available on the role of NUAK1 in atherosclerosis, and its precise role remains to be elucidated." (PMID 38892400, 2024).
autism (1 paper, 2024). Persistent deficits in social interaction and communication and interaction as well as a markedly restricted repertoire of activity and interest as well as repetitive patterns of behavior. "We previously identified the autism-linked kinase NUAK1 as a central regulator of axon branching through the control of mitochondria trafficking." (PMID 38514619, 2024).
brain cancer (1 paper, 2021). A primary or metastatic malignant neoplasm affecting the brain. "Additionally, NUAK1 and NUAK2 are altered in both ovarian and brain cancer." (PMID 34685740, 2021).
brain tumours (1 paper, 2024). "We should also be mindful that whilst the tissue itself is non-tumour, we cannot rule out alterations to NUAK1 expression or activity in these samples, which have originated from individuals with brain tumours." (PMID 38175261, 2024).
fluorosis (1 paper, 2023). "The top 10 drugs have been reported in previous studies, namely Celastrol, LDN-193189, XPNPEP1, GNB5, Importazole, LDHB, NUAK1, IFNG, IFNB1, and YWHAH, suggesting that these drugs may be effective candidate drugs for the treatment of fluorosis." (PMID 36835629, 2023).
ischemic stroke (1 paper, 2016). A stroke disorder caused by obstruction of blood flow to the brain, due to thrombotic (local blood clot formation) or embolic (due to a blood clot or other material traveling from another site) event. "NUAK1 is highly expressed in the cortex during embryonic development and promotes axon extension and branching, affecting neuronal differentiation, which might be a potential therapeutic approach for the repair of ischemic stroke." (PMID 27458373, 2016).
medullary breast carcinoma (1 paper, 2020). An infiltrating breast carcinoma with a relatively favorable prognosis. "Analysing the GSE21653 database, we investigated NUAK1 and miR-622 expression also in medullary breast cancer patients, and Kaplan–Meier disease-free survival curve showed that low level of NUAK1 is significantly correlated with disease-free survival (p = 0.02) (right)." (PMID 32418991, 2020). "In addition, analysing the GSE21653 database, we also found that in medullary breast carcinoma low level of NUAK1 significantly correlated with a higher disease-free survival probability." (PMID 32418991, 2020).
ovarian serous cystadenocarcinoma (1 paper, 2020). A malignant serous cystic epithelial neoplasm arising from the ovary. "Using The Cancer Genome Atlas (TCGA) ovarian serous cystadenocarcinoma dataset, we found a significant positive correlation (Pearson correlation: 0.63, p = 5.10 × 10−35) between NUAK1 and FN1 mRNA expression in tumours from EOC patients." (PMID 32429240, 2020).
renal fibrosis (1 paper, 2024). A final common manifestation of a wide variety of chronic kidney diseases characterized by glomerulosclerosis and tubulointerstitial fibrosis. "However, in the kidneys, it has been shown that silencing of NUAK1 reduces the expression of TGF-β1 and reversing fibrosis of renal tubular cells, thus alleviating the symptoms of renal fibrosis." (PMID 38774751, 2024).
skin tumor (1 paper, 2014). "In fact staining of human skin tumor SCC samples with LKB1 and NUAK1 showed an inverse Hscore correlation (95% confidence interval, P = 0.0033) between LKB1 and NUAK1 expression." (PMID 25329316, 2014).
triple-negative breast carcinoma (1 paper, 2023). An invasive breast carcinoma which is negative for expression of estrogen receptor (ER), progesterone receptor (PR), and human epidermal growth factor receptor 2 (HER2). "We analyzed TCGA data from triple-negative breast cancer (TNBC) and we found a positive correlation between NUAK1 and EGFR expression." (PMID 38135881, 2023).